BCL2 (BCL2 apoptosis regulator)
Diseases named in the same sentence as BCL2 in open-access papers (continued):
Sharing a sentence is not in itself a finding about the gene and the disease.
prostate carcinoma (continued). "Specifically, ART regulates the lncRNA UCA1/miR-184/BCL-2 axis, to inhibit prostate cancer, while the has-circ-0043256/miR-1252/ITCH axis was involved in the treatment of non-small cell lung cancer by CA." (PMID 31178721, 2019). "Percentage of Bcl-2 protein positive cells in prostate cancer, as determined by immunohistology in different studies." (PMID 31312616, 2019). "Other than inhibition of metastasis and cell proliferation, Dis induces apoptosis in prostate cancer cells through over expression of Bax, p27kip1 and Foxo3 and down regulation of Bcl-2 and c-Myc." (PMID 31295840, 2019). "This study provides a strong preclinical rationale for developing therapeutic strategies to target antiapoptotic BCL2 signaling in combination with AR antagonists to improve treatment options for patients with advanced prostate cancer." (PMID 31228231, 2019). "The apoptotic effect of pristimerin is related to Bcl-2, and it mediates down-regulation of Bcl-2 through reactive oxygen species (ROS)-dependent ubiquitin-proteasomal degradation pathway in human prostate cancer LNCaP and PC-3 cells." (PMID 31354475, 2019). "In a study, BCL2 over-expressers showed significantly better response to salvage radiotherapy compared to low-expressers in prostate cancer." (PMID 31426855, 2019). "This is supported by the observation in prostate cancer models that loss of BCL2, such as in the BCL2 null cell line (DU145), corresponds with resistance to paclitaxel, while a BCL2 expressing cell line (PC3) is sensitive to paclitaxel." (PMID 31013740, 2019). "Bcl-2 was mainly distributed in 6 pathways, which were small-cell lung cancer, prostate cancer, pathways in cancer, neurotrophin signaling pathway, focal adhesion, and colorectal cancer." (PMID 31781263, 2019). "Dis induces apoptosis in PC-3 human prostate cancer cells through overexpression of Bax, P27kip1 and Foxo3 and downregulation of Bcl-2 and c-Myc." (PMID 31295840, 2019). "Since Bcl-2 plays a role in autophagy, we further analyzed the TCGA database of prostate cancer patients and found the highest percentage of high-grade tumors in the cohort with low KLF5/high Bcl-2 levels." (PMID 31534497, 2019). "PAB also induced apoptosis via proteasome-mediated protein degradation of Bcl-2 in human prostate cancer DU145 cells." (PMID 31623058, 2019). "In LNCaP cells, AL treatment increased the ratio of BAX and Bcl-2, indicating induced apoptosis in this prostate cancer cell line." (PMID 31467577, 2019). "The active fraction exerted its anti-proliferative properties by increasing the expression of Bax and Smac/DIABLO (diablo IAP-binding mitochondrial protein) and downregulating the expression of Bcl-2 in PC3 prostate cancer cells, which leads to apoptosis." (PMID 30324012, 2018). "This pro-apoptotic action of miR-204 through BCL2 targeting was also shown in prostate cancer cells." (PMID 29382303, 2018). "Overexpression of bcl-2, a known antiapoptotic oncogene, seems to be critical in transforming prostate cancer cells from an androgen-dependent to an androgen-independent state." (PMID 30279956, 2018). "This tumor suppressive activity is associated with 18 kDa LOX-pp, which inhibited FGF-2 signaling in prostate cancer (PCa), oncogenic bcl-2 activity in breast cancer, and nuclear factor-κB (NF-κB) activation in lung and prostate carcinoma." (PMID 29732010, 2018). "Anti-apoptotic Bcl-2 is frequently upregulated in prostate cancer following androgen ablation therapy." (PMID 29362360, 2018). "Molecularly downregulation of NSBP1 resulted in decreased growth of cells and G2/M cell cycle arrest in prostate cancer, downregulation of Bcl-2 in ESCC and downregulation of B1 cyclin in ESCC and NSCLC." (PMID 29649113, 2018).
prostate carcinoma (continued). "The cytoplasmic Bcl-2 over-expression was found in prostate cancer specimens and predicted early tumor progression." (PMID 30321230, 2018). "In the present study, the expression ratio of BCL2/BAX was found to be significantly greater after Ang1–7 treatment in all prostate cancer cells." (PMID 30361641, 2018). "Specifically, viral E1A-expression sensitised the cells to mitoxantrone-mediated apoptosis and simultaneously attenuated mitoxontrone-induced autophagy in prostate cancer cells, only in the presence of Bcl-2." (PMID 29362360, 2018). "DATS treatment of orthotopically implanted prostate cancer cells in nude mice revealed an increased pro-apoptotic:anti-apoptotic signal ratio by modulation of Bax, Bak, Bcl-2, and Bcl-XL along with increased DR protein levels." (PMID 28788092, 2017). "The overall effect of the presumably low-expression BCL2-938 CC genotype resulted in strongly reduced survival rates in the present cohort of prostate cancer patients." (PMID 28396899, 2017). "Aim of the present study was to analyze the role of BCL2-938C>A genotypes in prostate cancer mortality." (PMID 28396899, 2017). "For example, miR-34 in prostate cancer cells and cell-derived exosomes targeted Bcl-2 to regulate the response to docetaxel." (PMID 29228644, 2017). "In a previous clinical trial (SELECT), the positive impact of Se plus vitamin E on human prostate carcinoma cell lines was demonstrated, showing an evident connection between Bax and Bcl-2 modulation and induction of apoptosis." (PMID 28327526, 2017). "Abnormal high expression of the Bad protein promoted prostate cancer growth, and anti-apoptotic molecular Bcl2 and pro-apoptotic molecular Bax constitute an apoptosis switch in cancer development and therapy." (PMID 28915591, 2017). "Bcl-2 and Bcl-xL protein levels are commonly elevated in prostate cancer cells, protecting them from apoptosis and reducing chemosensitivity." (PMID 27458171, 2017). "While miRNA deregulation has been associated with aberrant expression of BCL2, KRAS and PTEN in other type of cancers, further studies are needed to shed light on their role in prostate cancer." (PMID 29268752, 2017). "ROS production induced by the Pd complex treatment activated apoptosis through mitochondrial membrane depolarization in all prostate cancer cells, with up-regulation of Bax and down-regulation of Bcl-2 proteins." (PMID 28099141, 2017). "Our findings support the results of previous studies conducted on prostate cancer cells demonstrating down-regulation of Bcl-2 and Bcl-XL." (PMID 26260271, 2016). "miR-16 is decreased in prostate cancer, whereas the expression levels of its targets, namely Bcl-2, CCND1 and WNT3A, are inversely increased." (PMID 26655091, 2016). "Influences cell response to docetaxel in prostate cancer cells through regulation of anti-apoptotic BCL-2." (PMID 27517627, 2016). "In prostate cancer cells overexpressing the anti-apoptotic Bcl-2 protein, we reported that ER Ca2+ content was lowered." (PMID 27074561, 2016). "We further identified that the effects of CYP1A1 knockdown on increased apoptosis in prostate cancer cell lines were correlated with reduction of anti-apoptotic BCL2, the primary gatekeeper of the intrinsic (mitochondrial) apoptotic pathway." (PMID 27203547, 2016). "Baicalin induces cell cycle arrest and apoptosis of prostatic cancer cells, while licochalcone A acts as a phytoestrogen and modulates the expression of the pro-apoptotic protein Bcl-2." (PMID 26512639, 2015). "Our report shows, for the first time, that HGFL provides a survival advantage to prostate cancer cells through a Ron dependent pathway and that this effect is associated with the activation of STAT3 and Bcl2." (PMID 24980820, 2014). "Further study revealed that subditine induces Bcl-2 and Bcl-xL down-regulation in both prostate cancer cell-lines, indicating mitochondrial-mediated apoptosis pathway." (PMID 24551054, 2014).
prostate carcinoma (continued). "Other studies have demonstrated that intracellular Par-4 down-regulates Bcl-2 protein in neoplastic lymphocytes and at transcript level in prostate cancer cell lines." (PMID 24523904, 2014). "The Bcl-2 expression decreased in the exposure of fenofibrate in mantle cell lymphoma and prostate cancer cells as well." (PMID 24529079, 2014). "In vitro analysis demonstrated robust STAT3 activation resulting in Bcl2-dependent survival following treatment of prostate cancer cells with HGFL." (PMID 24980820, 2014). "ROS production was observed in dentatin-induced prostate cancer cells apoptosis accompanied by Bcl-2 and survivin downregulation." (PMID 25140197, 2014). "Bcl-2 overexpression plays a role in the development of androgen-independent prostate cancer cells, conferring resistance to apoptosis by an antagonistic effect in caspase 1 activation, providing resistance to radio and chemotherapies." (PMID 24629090, 2014). "In prostate cancer cell lines (PC-3-Neo and PC-3-Bcl-2 transfected with Bcl-2), treatment with CTCE-9908 reduces VEGFR1and CD11b expressing cells." (PMID 26932379, 2014). "The overexpression of bcl-2 has been identified in a variety of human cancers, including breast, colon, ovarian and prostate cancer." (PMID 24137369, 2013). "Our observations suggested that Akt, EGFR, Src, Bcl-2, and AR signaling pathways are potential therapeutic targets for AR-positive castration-resistant prostate cancers." (PMID 24349321, 2013). "Paclitaxel, androgen, and inhibitors for PI3K/Akt, EGFR, Src, or Bcl-2 seem to be potential choices for treatment of advanced prostate cancers." (PMID 24349321, 2013). "Increased Par-4 expression sensitizes PC-3 prostate cancer cells to radiation-induced apoptosis due to inhibition of NF-κB activity, with a consequent decrease in Bcl-2 expression." (PMID 23760770, 2013). "It induces apoptosis in Src inhibitor resistant prostate cancer cells, likely through a mechanism of down regulation of Myc and BCL2." (PMID 23967135, 2013). "This antiproliferative effect is associated with a decrease in the Bcl-2/Bax expression ratio and a decrease in the ratio of GSH/GSSG (essentially an oxidative state) in LAPC-4 prostate cancer cells." (PMID 23351141, 2013). "In prostate cancer PC-3cell line, bufalin-induced apoptosis can be largely attenuated by a miR-181a inhibitor, which blocked bufalin-induced Bcl-2 reduction and caspase-3 activation." (PMID 24267199, 2013). "Prostate cancer targeted therapy is a new approach in clinical trials and a number of studies including targeting angiogenesis, tubulin, and Bcl-2 to trigger apoptosis are being conducted." (PMID 24391668, 2013). "Up-regulation of Bcl-2 is necessary for the progression of LNCaP prostate cancer cells from an androgen-dependent to an androgen-independent growth stage." (PMID 24349321, 2013). "It is likely that NaB induces prostate cancer DU145 cell apoptosis by inhibiting bcl-2 expression and activating Bax." (PMID 24086397, 2013). "Both Bcl-xL and Bcl-2, antiapoptotic members of the Bcl family, were found in prostate cancer cell lines." (PMID 23951286, 2013). "Another study on prostate cancer revealed that an antitumor growth effect of Nuclear Factor kappa B (NF-κB) suppression in mice is crucially dependent on downregulation of Bcl-2 and Bcl-xL." (PMID 24098503, 2013). "Previous studies have shown the ability of NF-kB to promote cell growth and proliferation of prostate cancer cells via various mechanisms, including regulation of c-myc, cyclin D1, Bcl-2 and IL-6." (PMID 24062781, 2013).
prostate carcinoma (continued). "PD 98059 induces apoptosis that is mediated through inactivation of Bcl-2 due to increasing in phosphorylated Bcl-2 in human prostate cancer cells." (PMID 23670020, 2013). "In fact, forced expression of PTEN in prostate cancer cells sensitizes cells to radiation and downregulated Bcl-2 expression in two prostate cancer cell lines that over express Bcl-2, PC-3-Bcl-2 and LNCaP." (PMID 23351141, 2013). "In contrast, MSeA increased Bax and decreased Bcl-2 expression in three lines of prostate cancer cells." (PMID 24152862, 2013). "Androgens have been reported to repress Bcl-2 expression via activation of the retinoblastoma (RB) protein in prostate cancer cells." (PMID 24349321, 2013). "Overexpression of Bcl-2 protects LNCaP prostate cancer cells from apoptosis and confers resistance to androgen ablation treatment." (PMID 24349321, 2013). "Stable transfection of Bcl-2 into PC-3 prostate cancer cell line rendered these cells more radiation resistant than the parent PC-3 cells." (PMID 23351141, 2013). "It is also known that miR-16 regulates BCL2 expression and acts as a tumor suppressor in prostate cancer and chronic lymphocytic leukemia (CLL)." (PMID 22384141, 2012). "The resulting A10 aptamer-PLK1 or BCL2 siRNA chimeras induced specific silencing of target genes and cell death in prostate cancer cells expressing PSMA." (PMID 23130020, 2012). "In contrast, overexpression of Bcl-2 protected prostate cancer cells from MDA-7/IL-24-mediated apoptosis, suggesting Bcl-2 plays an important role in cancer cell apoptosis in response to MDA-7/IL-24." (PMID 22629368, 2012). "MiR-16 is often down-regulated in chronic lymphocytic leukaemia, gastric, ovarian and prostate cancers as a tumor suppressor that targets and down-regulates the anti-apoptotic gene BCL2." (PMID 22384141, 2012). "MiR-15a and miR-16-1 have been identified as tumor suppressor genes in prostate cancer, and are associated with the expression gene that promote the survival, proliferation, and invasion in prostate cancer cells, including Bcl2, CCND1, and WNT3 A." (PMID 23130020, 2012). "In advanced prostate cancer, for instance, miR-15a and miR-16 are significantly downregulated, whereas the expression of BCL2, CCND1 and WNT3A is concomitantly upregulated." (PMID 22583478, 2012). "Androgen-independent prostate cancer cells with higher levels of Bcl-2 were more resistant to (−)-gossypol induced apoptosis." (PMID 22363680, 2012). "Apoptosis resistance is associated with higher levels of bcl-2, and downregulation of bcl-2 sensitizes prostate cancer cells to undergo apoptosis." (PMID 22693649, 2012). "Direct evidence that loss of PTEN regulates cell survival is based on the observation that ectopic expression of PTEN in prostate cancer cells suppresses transcription of the anti-apoptotic molecule Bcl-2 via the cAMP response element-binding protein (CREB)." (PMID 24212771, 2011). "Recent reports have revealed the involvement of JNK-mediated Bcl-2 phosphorylation and degradation, and also the activation of caspase-9 in the apoptosis of both the androgen-dependent and -independent human prostate cancer cells." (PMID 21504622, 2011). "Cryptotanshinone, a major tanshinone, was found to sensitize DU145 prostate carcinoma cells to Fas-mediated apoptosis through suppressing Bcl-2 expression and augmenting Fas." (PMID 21274285, 2011). "Previous study has revealed that Bcl-2 is overexpressed in the progression to androgen-refractory prostate cancer." (PMID 21152091, 2010).
prostate carcinoma (continued). "NS-398 downregulated Bcl-2 expression in an androgen-sensitive human prostate cancer cell line LNCaP that exhibited a high constitutive level of COX-2." (PMID 20339581, 2010). "The role of Bcl-2 as an antiapoptotic molecule is significant in prostate cancer because of the level of tenacity and resistance it grants to a tumor." (PMID 19589167, 2009). "Among 20 men in the same study who were radio-recurrent and underwent prostatectomy for prostate cancer, 55% of the tumors were Bcl-2 immunopositive (p = 0.0004)." (PMID 19589167, 2009). "In those reports, the selective COX-2 inhibitor NS-398 was found to downregulate Bcl-2 in LNCaP prostate cancer cells; another COX-2 inhibitor, celecoxib, downregulated Bcl-2 in K562 chronic myeloid leukemia cells and in MPP89 malignant mesothelioma cells." (PMID 17612393, 2007). "In prostate cancer models, Bcl-2 antisense oligonucleotides inhibited the expression of Bcl-2, delayed the development of androgen independence and enhanced the effects of chemotherapy." (PMID 16983403, 2006). "We then examined the Bcl-2 and Bcl-xL proteins expression in quercetin treated prostate cancer cells, we observed significant decrease of Bcl-2 and Bcl-xL proteins." (PMID 16600019, 2006). "Conversely, in a model of androgen withdrawal from prostate cancer cells, NF-κB activation induced BCL-2 gene transcription." (PMID 12865934, 2003). "Bcl-2 protein is one of the key inhibitors of apoptosis and is often unregulated in advanced prostate cancer." (PMID 9514052, 1998). "In prostate cancer models, 14a inhibited AR- and AR+ cell proliferation, enhanced histone and tubulin acetylation, upregulated p21, and downregulated Bcl-2." (PMID 42059134, 2026). "Castration and enzalutamide induce BCL-2 to drive therapy resistance in prostate cancer (PCa)." (PMID 41315064, 2025). "Experiments in LNCaP cells (androgen-responsive prostate cancer) have shown that Bcl-2 is essential for both the survival of androgen-independent prostate cancer cells and the transition of prostate cancer cells from androgen-dependent to androgen-independent states." (PMID 40661148, 2025). "(2022), that reported a pro-apoptotic Bax/Bcl-2 shift in PHY-treated prostate cancer cells." (PMID 40469194, 2025). "Additionally, an inverse correlation between SIRT1 and miR-34a expression was observed in prostate cancer, which led to drug resistance through the BCL2 pathway." (PMID 40149537, 2025). "Additionally, in prostate cancer it has been shown that NOTCH1 silencing decreased BCL-2 levels which increased sensitivity to chemotherapy, suggesting a similar mechanism for the interplay of AZ1 and venetoclax." (PMID 40456839, 2025). "In addition, decreased expression of Su(H) can significantly inhibit cell growth via suppression of its target genes CDK2, CDK4, CyclinD1, and Bcl-2, and upregulation of P21 and P27 to induce cell cycle arrest in prostate cancer cells." (PMID 40151788, 2025).